ADAM17 (ADAM metallopeptidase domain 17)
Diseases named in the same sentence as ADAM17 in open-access papers (continued):
Sharing a sentence is not in itself a finding about the gene and the disease.
glioma (36 papers, 2008 to 2025). A benign or malignant brain and spinal cord tumor that arises from glial cells (astrocytes, oligodendrocytes, ependymal cells). "Collectively, our data show that ADAM17 levels are linked to the advancement of malignancy and inferior clinical outcomes in individuals diagnosed with glioma." (PMID 37175410, 2023). "Similar changes in TACE/ADAM-17 activity were also found in high-grade glioma cells being associated with tumor progression and poor prognosis." (PMID 32326230, 2020). "Using gain- and loss-of-function studies, we showed that FoxM1/ADAM17 axis promoted the MES transition in glioma cells." (PMID 29700308, 2018). "The association between ADAM17, the malignancy of the glioma and the clinicopathological factors were determined." (PMID 25364437, 2014). "We found that ectopic expression of miR-145 in U87 and U251n glioma cells caused decreased proliferation, migration and invasion with accompanying low protein expression of ADAM17 and EGFR." (PMID 23076445, 2013). "ADAM17 has already been discussed as a valuable diagnostic and prognostic biomarker for colorectal cancer metastasis, early-stage ovarian cancer, and malignant CNS tumors." (PMID 36293469, 2022). "ADAM17 may have an important oncogenic function in glioma progression, and is a potential diagnostic and therapeutic target." (PMID 25364437, 2014). "In addition, the association of ADAM17 expression with the clinicopathological parameters and the survival rates of the glioma patients was analyzed." (PMID 25364437, 2014). "The present study analyzed ADAM17 expression in normal and glioma brain tissue, and investigated the association between the ADAM17 expression level and the malignancy and prognosis observed in glioma patients." (PMID 25364437, 2014). "However, ADAM17 expression was significantly associated with the glioma WHO histological grade (P<0.05)." (PMID 25364437, 2014). "Inhibitory anti-ADAM17 monoclonal antibodies (mAbs) abrogate the cleavage of p75 in a neuroblastoma-glioma cell line." (PMID 40132887, 2025). "The expression or activity of ADAM17 in glioma cells was positively correlated with the expression of sLRIG3 in cell supernatant." (PMID 36639372, 2023). "ADAM17 was upregulated in high-grade glioma tissues compared to that in low-grade and normal brain tissue from patients with glioma and, thus, has a diagnostic and prognostic value in patients with this malignancy." (PMID 37175410, 2023). "A marked increase in ADAM17 protein levels was noted in glioma tissues compared with those in normal brain tissue." (PMID 37175410, 2023). "ADAM17 has been reported to promote the malignant phenotype of glioma cells by increasing proliferation, invasion, angiogenesis, and tumor growth." (PMID 37175410, 2023). "In glioma, Sp1 promotes proliferation and invasion of glioma cells via upregulating oncogenes, such as ADAM17 and MDK48,49." (PMID 35778451, 2022). "Hypoxia-induced SP1 expression led to increased activation of disintegrin and metalloproteinase-17 (ADAM17) promoter, enhancing glioma’s invasiveness under hypoxic conditions." (PMID 36077352, 2022). "Fitting our data, ADAM10 and ADAM17 (over) expression levels likewise significantly correlates with tumor grade in glioma, and both ADAMs are discussed as prognostic markers and therapeutic targets." (PMID 36293469, 2022). "The researchers revealed that ADAM17 promotes glioma cell proliferation, invasion and angiogenesis in vitro, and glioma cell growth in an animal model." (PMID 34638718, 2021). "In addition, ADAM17 is correlated with a high tumor grade and poor prognosis in patients with glioma and may be a potential diagnostic and therapeutic target, whereas ADAM10 is associated with glioma grade in glioma growth and development, particularly the invasiveness of the glioma." (PMID 34638718, 2021).
glioma (continued). "Other hypoxia-activated ADAM17 substrates have previously been shown to accelerate tumor progression in mouse models of glioma." (PMID 32205867, 2020). "In order to verify the effects of ADAM17 on MES transition in glioma cells, we first knocked down ADAM17 in U251MG and U87MG cells, and then investigated the biology behavior." (PMID 29700308, 2018). "Whereas ADAM17 played similar roles in inducing malignant phenotype of glioma cells, mostly restricting to shedding of ErbB ligands such as activating EGFR signaling pathway." (PMID 29700308, 2018). "To investigate the association of FoxM1 and ADAM17 with the MES phenotype, we first analyzed the expression levels of FoxM1, ADAM17 and mesenchymal markers in glioma specimens from The Cancer Genome Atlas (TCGA)." (PMID 29700308, 2018). "Some recent studies have shown that ADAM17 overexpression was correlated with high tumor grade and poor prognosis in glioma patients." (PMID 29700308, 2018). "In glioma cells and glioma-bearing nude mice, targeting ADAM17 with TAPI-2 (an ADAM17 inhibitor) or siRNA, can significantly attenuate tumor growth and invasiveness, compared to their untreated counterparts." (PMID 27803674, 2016). "By up-regulating the ligands of EGFR, ADAM17 can promote glioma cells malignant phenotype by increased proliferation, invasion, and angiogenesis." (PMID 27803674, 2016). "The ADAM17 protein expression in the eight control and 60 glioma cases was detected by IHC staining." (PMID 25364437, 2014). "In the present study, the expression pattern and prognostic significance of ADAM17 was investigated in patients with glioma." (PMID 25364437, 2014). "The results showed that ADAM17 was upregulated in the high-grade glioma tissues compared with that in the low-grade and normal brain tissues of the glioma patients, and that the level increased with ascending World Health Organization tumor grade (P<0.05)." (PMID 25364437, 2014). "In order to study the role of ADAM17 expression in glioma, the expression of the protein was analyzed in 60 patients with glioma and in eight control cases (patients with traumatic brain injury) by western blotting and immunohistochemistry (IHC)." (PMID 25364437, 2014). "The strong positive expression rate of ADAM17 in the control, low-grade glioma and high-grade glioma groups was 0, 0.4 and 51.43%, respectively." (PMID 25364437, 2014). "The expression level of ADAM17 in the high- and low-grade gliomas was significantly higher compared with that of the control brain tissue (P<0.05)." (PMID 25364437, 2014). "The positive rate of ADAM17 expression in the glioma patients of all grades was 88.33%, whereas it was only 37.5% in the control group." (PMID 25364437, 2014). "ADAM17 was of particular interest because our previous studies revealed that its expression level was upregulated in glioma specimens." (PMID 23076445, 2013). "In conclusion, our data suggested that miR-145 plays a key role in the malignancy of glioma cells possibly by direct regulation of ADAM17 protein expression, which affects glioma cell proliferation, migration and invasion." (PMID 23076445, 2013). "Ectopic expression of ADAM17 induced tumorigenicity of cortical astrocyte cell line and promotes both breast and glioma cell malignant phenotypes." (PMID 23076445, 2013). "Our previous study showed that high level expression of ADAM17 was found in high grade glioma samples." (PMID 23076445, 2013). "ADAM17 and EGFR have been reported to play important roles in glioma, and overexpression of ADAM17 promotes glioma invasiveness." (PMID 23076445, 2013). "Hypoxic-induced ADAM17 expression is dependent upon Sp1, and ADAM17 significantly contributes to hypoxic-induced glioma invasion." (PMID 19772640, 2009).
glioma (continued). "In this study, we investigated if Sp1 protein plays a role in ADAM17 transcription, and if Sp1 regulates hypoxic-induced ADAM17 expression in U87 human glioma cells." (PMID 19772640, 2009). "Here we demonstrate that Sp1 is critical for hypoxic-induced ADAM17, and that Sp1 contributes to hypoxic induced glioma invasion." (PMID 19772640, 2009). "Importantly, we demonstrate the ability of inhibitory anti-ADAM17 mAbs to abrogate the cleavage of p75 in a neuroblastoma-glioma cell line and reverse the neurite outgrowth inhibition by myelin-associated inhibitors." (PMID 40132887, 2025). "Similarly, ADAM17 activates the EGFR-PI3K-AKT pathway in glioma, resulting in enhanced proliferation, invasion, and angiogenesis, and inhibition of ADAM17, which significantly reduce tumour growth in mice." (PMID 40427200, 2025). "Furthermore, research has demonstrated that GA at concentrations up to 125 μg/mL can inhibit angiogenesis in glioma and cervical cancer cells by downregulating the signaling pathways of ADAM metallopeptidase domain 17 (ADAM17), Akt, ERK, and EGFR." (PMID 39199245, 2024). "While miR-145 can suppress ADAM17 expression in glioma cells, thereby inhibiting cell migration and invasion, whether miR-145 enhances TMZ sensitivity in GBM by regulating ADAM17 remains uncertain." (PMID 37175410, 2023). "However, upregulating ADAM17 or using ADAM17 agonist PMA significantly increased the protein level of sLRIG3 in supernatant of glioma cell lines." (PMID 36639372, 2023). "ADAM17 expression increases with the pathological progression of glioma." (PMID 37175410, 2023). "Furthermore, we tested the expression of α-disintegrin and metalloprotease-17 (ADAM17) in glioma tissues and found that the expression of ADAM17 decreased with the reduction in NCAPG expression." (PMID 35372056, 2022). "Overall, we can conclude that the expression of NCAPG in glioma is relatively high, and that the expression of MHC-I molecules and ADAM17 in glioma cells is also elevated, thereby inhibiting the activation of NK cells, resulting in immune escape and decreased patient survival." (PMID 35372056, 2022). "Among these proteins, we identified Disintegrin and metalloproteinase domain-containing protein 17 (Adam17), known to promotes glioma cell malignant phenotype and Branched-chain-amino-acid aminotransferase (Bcat1) which promotes cell proliferation in glioma." (PMID 33402730, 2022). "In addition, our study demonstrated that the expression of ADAM17 in the glioma cell lines was positively correlated with the expression of NCAPG." (PMID 35372056, 2022). "Additionally, external factors such as hypoxia have been shown to induce ADAM17 expression within human glioma cells by promoting Sp1 mediated transcription of the Adam17 gene." (PMID 33904577, 2021). "Furthermore, FoxM1/ADAM17 axis promoted the tumorigenicity of glioma cells and the progression of GBM." (PMID 29700308, 2018). "Overexpressing FoxM1 or ADAM17 increased the mesenchymal phenotype of glioma cells, which could be reversed by silencing FoxM1 or ADAM17." (PMID 29700308, 2018). "To ascertain whether FoxM1 regulate MES transition in glioma cells in an ADAM17-dependedent manner, we first knocked down ADAM17 expression in FoxM1 overexpression cells." (PMID 29700308, 2018). "Notably, it was the first time to demonstrate that there was a direct link between FoxM1 and ADAM17: FoxM1 binding to the promotor of ADAM17 to regulate its expression, which even elucidated a mechanism for overexpression of ADAM17 in glioma." (PMID 29700308, 2018). "In addition to ADAM9, several other members of the ADAM family have also been implicated in tumor growth and invasiveness of gliomas, such as ADAM10, ADAM12 and ADAM17." (PMID 27571068, 2016). "Furthermore, low expression of miR-145 in glioma cells was correlated to increased ADAM17 and EGFR expression." (PMID 25544346, 2015). "miR-145-5p directly targets ADAM17 mRNA and inhibits glioma cell proliferation and invasion." (PMID 25544346, 2015).
glioma (continued). "However, decreased miR-145 expression promoted U87 glioma cell proliferation, invasion and angiogenesis, and reduced-expression of miR-145 increased ADAM17 and EGFR expression in U87 cells." (PMID 25544346, 2015). "Furthermore, we examined the mechanisms by which ADAM17/EGFR/MAPK/ERK pathway contributed to miR-145-induced inhibition on glioma proliferation, invasion, and angiogenesis after transfection of miR-145." (PMID 25544346, 2015). "Overall, the present study hypothesized that ADAM17 is highly expressed in glioma, and that its expression is correlated with malignant glioma." (PMID 25364437, 2014). "The expression pattern of ADAM17 in glioma patients, however, is unclear." (PMID 25364437, 2014). "The glioma patients were divided into two subgroups, a high expression group (>45% positive cells) and a low expression group (<45% positive cells), according to the IHC ADAM17 expression data." (PMID 25364437, 2014). "However, further study is needed to determine if ADAM17 activity is influenced by miR-145 in vivo in glioma." (PMID 23076445, 2013). "Taken together with reduced p-Erk expression, miR-145 transfection may decrease glioma cell migration and invasion through ADAM17/EGFR/ERK signaling pathway." (PMID 23076445, 2013). "ADAM17 contributes to hypoxic-induce invasiveness of glioma." (PMID 19772640, 2009). "Our findings suggest the Sp1 transcription factor mediates ADAM17 expression under hypoxia, regulates glioma invasiveness, and thus, may be a target for anti-invasion therapies." (PMID 19772640, 2009). "Hypoxia induces expression of ADAM17 and increases invasiveness of glioma in vitro." (PMID 19772640, 2009). "Therefore, ADAM17 is a potential malignant biomarker for gliomas." (PMID 37175410, 2023). "Thus, the authors investigated whether ADAM17 contributes to glioma progression and assessed its role in the invasion and proliferation of human glioma cells in vitro and tumor growth in vivo." (PMID 34638718, 2021). "Furthermore, ADAM17 knockdown downregulated mesenchymal markers expression and elicited E-cadherin expression, which is consistent with the results of FoxM1 knockdown in glioma cells." (PMID 29700308, 2018). "We next confirmed whether the FoxM1/ADAM17 axis regulated the tumorigenicity of glioma cells." (PMID 29700308, 2018). "Thus, we examined the effects of FoxM1 on ADAM17 mRNA and protein expression in glioma cells." (PMID 29700308, 2018). "Similarly, it was suggested that ADAM17 was also critical for the MES transition in glioma cells." (PMID 29700308, 2018). "Given that ADAM17 enhances cell invasion and the degree of malignancy by activating EGFR in a variety of tumor cells, we propose that ADAM17 may have the same role as an oncogene in glioma, however, the underlying mechanism remains to be investigated." (PMID 25364437, 2014). "Thus, the reduction of miR-145 in glioma cells yields an increased expression of ADAM17." (PMID 23076445, 2013). "It has been shown that Ph-PDT can induce the ADAM17–EGFR–PI3K–Akt pathway in healthy brain tissue, leading to an increase in the EGFR in both healthy cells and subsequently implanted glioma cells, significantly increasing the U87 cell invasion in nude mice." (PMID 39201395, 2024). "Since miR-145 can target ADAM17 to downregulate its expression, we searched the CGGA database for the expression of miR-145 in primary and recurrent gliomas." (PMID 37175410, 2023). "According to a recent study, a monoclonal antibody against ADAM17, D8P1C1, effectively inhibited the proliferation of breast, ovarian, glioma, colon, and lung adenocarcinoma cells." (PMID 37175410, 2023). "Therefore, ADAM17 may be a potential blood biomarker for glioma staging." (PMID 37175410, 2023). "Several studies reported that ADAM9, ADAM10, and ADAM17 showed high expression in glioma; meanwhile, ADAM9, as a potential regulator of glioma invasion, showed higher expression in GBM compared with LGG." (PMID 36172139, 2022).
glioma (continued). "Our results show that X-ray irradiation induced the expression of Notch signaling components such as Notch receptors, target genes, and ADAM17 activity, while CII reduced it in glioma cell lines." (PMID 36359750, 2022). "Similar observations have also been seen with glioma stem-like cells, with ADAM10- and ADAM17-dependent shedding of ULBP2." (PMID 33352921, 2020). "Subsequently, we analyzed the expression levels of FoxM1, ADAM17 and mesenchymal markers (vimentin, YKL-40) in four glioma cell lines." (PMID 29700308, 2018). "We show here a positive correlation between stem/progenitor cells and fibronectin in high grade glioma tissues, as well as an increase in GSC migration through fibronectin during ADAM10 and ADAM17 inhibition, as previously shown with renal cancer cells." (PMID 27541285, 2017). "Western blotting showed that the expression of ADAM17 in the high-grade (WHO III–IV; 1.292±0.140) and low-grade (WHO I–II; 0.823±0.101) glioma groups were significantly higher compared with the control brain tissue (0.325±0.068)." (PMID 25364437, 2014). "In our present study, we demonstrated that miR-145 is an important regulator of ADAM17, and directly binds the 3′-UTR of ADAM17 mRNA in glioma cells." (PMID 23076445, 2013). "Interestingly, the membrane-bound metalloprotease, ADAM17, is capable of promoting the cleavage of intracellular CD44 and enhanced stemness in glioma cells via the activation of HIF-2α signaling." (PMID 40191733, 2025). "Moreover, sublethal PDT induces an increase in the HIF-1α expression in healthy brain tissue as well, stimulating the expression of the ADAM17–EGFR–PI3K–Akt pathway and increasing the invasion of subsequently implanted glioma cells." (PMID 39201395, 2024). "ADAM17 overexpression is correlated to more advanced tumor stages and negative outcome in patients with glioma." (PMID 37175410, 2023). "ADAM17 and MAML3 are indexed in the KEGG “Notch signaling pathway”, and BMP2 and SMAD5 are indexed in the KEGG “TGF-beta signaling pathway”, which confirms our data on the involvement of these processes in the formation of glioma neurospheres." (PMID 36231068, 2022). "Additionally, studies on malignant glioma cells revealed that only ULBP2 was shed via ADAM10 and ADAM17 activity." (PMID 33352921, 2020). "The mechanisms involved in regulating DLK1 cleavage by ADAM17 appear to be complex, as we did not detect the intracellular fragment in four tested glioma cell lines in hypoxia." (PMID 32205867, 2020). "Our data indicate that TACE/ADAM-17 activity changes in patients with high-grade gliomas not only in tumor cells, but also in immune cells." (PMID 32326230, 2020). "Mechanistically, FoxM1/ADAM17 axis activated the EGFR/AKT/GSK3β signaling pathway and ADAM17/EGFR/GSK3β axis could maintain FoxM1 stability in glioma cells." (PMID 29700308, 2018). "The negative expression rate of ADAM17 in the control group was 62.5%, whereas it was only 0.29% in the high-grade glioma group." (PMID 25364437, 2014). "To test whether miR-145 suppresses the expression of ADAM17 and EGFR at protein level in glioma, we performed Western blot analysis." (PMID 23076445, 2013). "ADAM17 may also promote the cleavage of intracellular CD44 and enhanced stemness in glioma cells." (PMID 40191733, 2025). "Furthermore, the expression pattern of ADAM17 in relation to GBM progression was investigated by analyzing RNA sequencing data obtained from the CGGA dataset, which were grouped according to the WHO glioma grades." (PMID 37175410, 2023). "ADAM17 is an important member of the ADAM family and involved in proteolysis of collagen IV of the extracellular matrix and also the release from the cell surface of several integrins, suggesting that ADAM17 influences the invasive activity of different cells including glioma cells." (PMID 23076445, 2013). "However, whether ADAM17 is highly expressed in glioma is not known." (PMID 25364437, 2014).